U6 (U6 spliceosomal RNA )
Synonyms: LOC124903092
Gene: Small nuclear RNA gene on chromosome 12 (45,554,590 to 45,554,659, reverse strand). Ensembl gene ENSG00000283545.
Gene Ontology:
Molecular function: U4 snRNA binding
Biological process: formation of quadruple SL/U4/U5/U6 snRNP; spliceosomal tri-snRNP complex assembly
Cellular component: U4/U6 x U5 tri-snRNP complex; U6 snRNP
Homologues: Orthologues: dog U6 (97% identical), mouse Gm25805 (94% identical), rat LOC120096366 (81% identical). Paralogues in human: RNU6-1 (100% identical), RNU6-11P (100% identical), RNU6-2 (100% identical), RNU6-25P (100% identical), RNU6-37P (100% identical), RNU6-3P (100% identical), RNU6-4P (100% identical), RNU6-5P (100% identical), RNU6-6P (100% identical), RNU6-7 (100% identical), RNU6-8 (100% identical), RNU6-9 (100% identical), and 1286 more.